RNU6-365P (RNA, U6 small nuclear 365, pseudogene)
Gene: Small nuclear RNA gene on chromosome 11 (41,122,907 to 41,123,012, reverse strand). Ensembl gene ENSG00000252922.
Homologues: Orthologues: chimpanzee U6 (99% identical), macaque U6 (91% identical), pig U6 (63% identical). Paralogues in human: RNU6-354P (77% identical), RNU6-610P (77% identical), RNU6-21P (76% identical), RNU6-128P (75% identical), RNU6-266P (75% identical), RNU6-333P (75% identical), RNU6-552P (75% identical), RNU6-737P (75% identical), RNU6-1249P (75% identical), RNU6-12P (75% identical), RNU6-13P (75% identical), RNU6-144P (75% identical), and 1289 more.